IL6 (interleukin 6)
Diseases named in the same sentence as IL6 in open-access papers (continued):
Sharing a sentence is not in itself a finding about the gene and the disease.
medulloblastoma (16 papers, 2011 to 2025). A malignant, invasive embryonal neoplasm arising from the cerebellum. "We have shown that LLL12B inhibited IL-6-induced STAT3 phosphorylation in human medulloblastoma cells." (PMID 36009550, 2022). "Because IL-6 and IL-23 are cytokines closely related to IL-17, we also examined the expression levels of IL-6 and IL-23 in the medulloblastoma xenografts by real-time PCR and Western blot to investigate the microenvironment changes induced by IL-17." (PMID 26684834, 2015). "IL6 has been shown to promote medulloblastoma cell viability, proliferation, and glycolysis." (PMID 39857430, 2025). "In particular, the interleukin-6 (IL6)/gp130/Janus kinase (JAK)/signal transducer and activator of transcription 3 (STAT3) signaling pathway has been implicated in the development of chemoresistance to vincristine in group 3 medulloblastomas." (PMID 37568705, 2023). "So, IL-6 and IL-23 might provide protection to athymic nude mice against medulloblastomas in our current data." (PMID 26684834, 2015). "Furthermore, our study showed that injecting IL-17 significantly increased the IFN-gamma, IL-6, IL-23, Ccl2, and Ccl20 chemokine productions in medulloblastoma xenografts in vivo." (PMID 26684834, 2015). "Multiple factors have been identified as STAT3 signaling promoters, including IL-6 and LIF which are over expressed in medulloblastomas." (PMID 28035977, 2016). "Daoy medulloblastoma cells had a distinct chemokine signature, producing MCP-1; Gro-α; MIF; IL-8; Serpin E1; and IL-6." (PMID 21647415, 2011). "In G3 medulloblastoma, autocrine IL6 signaling activates the STAT3 pathway, contributing to drug resistance; thus, targeting the IL6/STAT3 axis has been proposed as a therapeutic strategy for G3 medulloblastoma." (PMID 39857430, 2025). "As a result, gp130 inhibitors (SC144 or bazedoxifene) and a JAK inhibitor (ruxolitinib) were individually investigated at non-cytotoxic doses and resulted in overcoming the acquired IL6-mediated resistance to vincristine in group 3 medulloblastomas." (PMID 37568705, 2023). "Together these data show that Stat3 is required for SHH signaling and that IL-6 expression is elevated in males which enhances SHH signaling and may contribute to the Stat3 and sex-dependent onset of medulloblastoma." (PMID 31683879, 2019). "We speculated that IL-17 might promote IFN-gamma, IL-6, IL-23, CCL-20, and Ccl2 expressions in the subcutaneous medulloblastoma model." (PMID 26684834, 2015).
Mycoplasma pneumoniae pneumonia (16 papers, 2016 to 2025). Interstitial pneumonia caused by extensive infection of the lungs (lung) and bronchi, particularly the lower lobes of the lungs, by mycoplasma pneumoniae in humans. "For instance, IL-6 levels have been found to increase in MERS patients associated with Mycoplasma pneumonia, suggesting that IL-6 might play a role in the occurrence of MERS." (PMID 40718417, 2025). "IL-6 was associated with the severity of mycoplasma pneumoniae pneumonia (MPP)." (PMID 32393186, 2020). "In mycoplasma pneumonia, Montelukast lowered serum IL-6, IL-17, and peripheral blood Th1 and Th17 levels." (PMID 35928365, 2022). "Mycoplasma pneumonia and streptococcal lower respiratory tract infections showed elevated levels of IL-6 compared to RSV." (PMID 33066100, 2020). "Mycoplasma pneumoniae pneumonia has an increase of neutrophils and IL-6, especially in severe group." (PMID 28589151, 2017). "Compared to acute stage, a decreased percentage of neutrophils and IL-6 level was observed at the recovery stage in children with severe Mycoplasma pneumoniae pneumonia." (PMID 28589151, 2017). "Moreover, ATF3 can inhibit the release of inflammatory factors TNF‐α, IL‐1β, IL‐6, and IL‐18 induced by Mycoplasma pneumonia." (PMID 37385291, 2025). "In addition, the production of IL-2, IL-4, IL-10, and IFN-γ by splenic lymphocytes has been detected in significant high levels in a gnotobiotic mice model of Mycoplasma pneumoniae pneumonia, and IL-1ß and IL-6 were upregulated in a novel mouse model immunized with MP extracts plus alum." (PMID 30305831, 2018). "The purpose of this study is to evaluate the efficacy of Vitamin A (VitA) as an adjuvant therapy for pediatric Mycoplasma Pneumoniae Pneumonia (MPP) through meta-analysis, and to investigate its impact on inflammation levels (IL-6, IL-10), in order to explore the role of VitA in pediatric MPP." (PMID 38859981, 2024). "The cytokines tumor necrosis factor-alpha, interleukin-8, interleukin-6, and interleukin-1 beta were detected in the airway secretions of children infected with RSV and Mycoplasma pneumonia, which may act as a double whammy of respiratory pathogens and correlate with severe pathogenesis." (PMID 36422931, 2022).
oral diseases (16 papers, 2015 to 2025). "IL-6 is a cytokine involved in inflammatory responses and has been implicated in various oral diseases." (PMID 40243946, 2025). "Irwin and Myrillas48 suggest IL-6 may play both an immunopathogenic pathogenic and protective role in oral disease." (PMID 39966408, 2025). "The non-invasive nature of salivary IL-6 measurement makes it a superior tool, offering great utility in mass screening efforts, especially within populations with a heightened prevalence of potentially malignant oral disorders linked to tobacco use." (PMID 38803729, 2024). "Monitoring salivary IL-6 levels can therefore serve as a useful biomarker for diagnosing and assessing the severity of oral diseases, enabling more targeted and effective treatment strategies to maintain and improve oral health." (PMID 40002706, 2025). "The most important salivary inflammatory biomarkers linked to oral disorders include matrix metalloproteinases (MMP-8 and MMP-9), tissue inhibitors of metalloproteinase, interleukins (IL-1, IL-6, and IL-8), and tumor necrosis factor (TNF-α)." (PMID 38535833, 2024). "IL-6 and IL-8 were also described as potential predictors for oral diseases, reinforcing the importance of evaluating the salivary levels of these biomarkers." (PMID 33717115, 2021). "Oral disease cause elevated levels of cytokines, especially tumour necrosis factor (TNF-a) and interleukin-6 (IL-6)." (PMID 25926988, 2015). "Conversely, lower IL-6 levels could suggest a diminished inflammatory response, potentially affecting the progression of oral diseases." (PMID 40243946, 2025). "With biomarkers like IL-1β, IL-6 and TNF-α helpful in determining theinflammatory status in oral disorders, the dynamic nature of saliva permits immediate tracking of progressing illness and therapyresponses." (PMID 40230914, 2024). "Interferon (IFN)-γ, IL-4, IL-6, IL-8, regulated on activation-normal T cell expressed and secreted (RANTES), stem cell factor (SCF), and monocyte chemoattractant protein (MCP) -1 were significantly lower on day 6 than on day 0 in cats with severe oral disease." (PMID 30822336, 2019).
osteonecrosis (16 papers, 2017 to 2026). A none disease characterized by death of bone tissue due to a lack of blood supply. "IL-6- or IL-1α/β-deficient mice were also significantly resistant to osteonecrosis development in this model." (PMID 28387378, 2017). "In fact, we demonstrate that TNFα-, IL-1α/β- or IL-6-deficient mice as well as wild-type mice administered a TNFα-inhibitor were significantly resistant to development of osteonecrosis accompanying infectious myelitis, even under bisphosphonate treatment." (PMID 28387378, 2017). "Interestingly, osteonecrosis induced by infectious osteomyelitis plus alendronate administration was significantly blocked in either IL-1α/β (IL-1 KO)- or IL-6-deficient (IL-6 KO) mice, and was weakly attenuated in IL-17A/F-deficient (IL-17 KO) mice." (PMID 28387378, 2017). "They found that inhibiting IL-6 by tocilizumab can inhibit bone resorption and promote bone regeneration and vascular regeneration, thus promoting the repair of osteonecrosis." (PMID 38622659, 2024). "Other studies have shown that in an animal model of femoral head osteonecrosis, inhibiting the proinflammatory factor interleukin-6 can inhibit bone resorbtion and promote bone regeneration and vascular regeneration, thus promoting the repair of osteonecrosis." (PMID 38622659, 2024). "Deletion of the proinflammatory cytokine IL-6 can stimulate osteogenesis during bone repair following osteonecrosis." (PMID 38622659, 2024). "We also demonstrated that NONFH is a chronic inflammatory disease involving persistent enrichment with IL-6 and IL-1β, osteonecrosis and fibrosis in the local lesion." (PMID 35573242, 2022). "Osteonecrosis by infectious osteomyelitis and elevation of the inflammatory factors C-reactive protein and IL-6 promoted by P. gingivalis s were also significantly reduced in the presence of silver-coated rods." (PMID 36319854, 2022). "In the piglet model of ischemic ONFH, IL-6 inhibitors inhibit osteoclastogenesis and delay progression of osteonecrosis, further highlighting the important role of IL-6 in the chronic inflammation of osteonecrosis." (PMID 35573242, 2022). "Previous studies have shown that inflammatory cytokines are increased during the development of steroid-induced osteonecrosis, such as IL-1, IL-2, IL-4, IL-6, IL-10, GM-CSF, IFN-γ, and TNF-α." (PMID 28167850, 2017). "Instead, we show that osteonecrosis development in infectious osteomyelitis mice administered alendronate was significantly blocked by gene targeting of either TNFα-, IL-6 or IL-1α/β, or by treatment with a TNFα inhibitor." (PMID 28387378, 2017). "Overall, these findings suggest that surfactin suppresses LPS-induced IL-6 expression in macrophages and inhibits osteonecrosis induced by bisphosphonate preparations and LPS through negative regulation of the JNK-c-Jun-AP-1 axis and inhibition of the JAK/STAT pathway." (PMID 41683585, 2026). "Interestingly, our results are similar to those reported for patients with drug-induced osteonecrosis, who show increased IL-6 levels in the local lesion and/or in the circulation." (PMID 35573242, 2022). "The administration of anti-inflammatory IFN-β could inhibit IL-6 secretion and suppress osteonecrosis." (PMID 33451334, 2021). "Moreover, high levels of inflammatory factors such as IL-6 and IL-21 could also aggravate the symptom of osteonecrosis." (PMID 35035862, 2022). "In the current study, the TLR4/NF-κB pathway and inflammation (IL-6, IL-10, and TNF-α) significantly increased after osteonecrosis induction by LPS with MPS." (PMID 28931847, 2017). "The blood chemistry data in the model group internal system revealed that the expression levels of both anti-and proinflammatory factors (IL-6, IL-10, and TNF-α) significantly increased after osteonecrosis induction, especially at 2 and 6 weeks." (PMID 28931847, 2017).
rectal cancer (16 papers, 2010 to 2026). A primary or metastatic malignant neoplasm that affects the rectum. "Several cytokines, including interleukins and interferons, and other mediators of inflammation were associated with both colon (INFGR1, IL6, IRF2, NFκB1A, TLR2) and rectal cancer survival (IL1A and IL3), as was suppressor of cytokine signaling (SOCS1)." (PMID 25541970, 2014). "In summary, the extent of CRT resistance in human rectal cancer cells could be tuned in both directions by manipulating the activity of the IL6/STAT3 signaling pathway." (PMID 33530306, 2021). "Our findings suggest that polymorphisms in IKBKB, IL6, and NFKB1 may jointly interact to influence colon and rectal cancer risk through an inflammation-related pathway." (PMID 21129206, 2010). "While our study focused on the prognostic value of NLR, PLR, and CEA, previous research has identified other serum biomarkers, including IL-6, TNF-αR2, adiponectin, and C-reactive protein as potential indicators of prognosis in rectal cancer." (PMID 41154438, 2025). "In rectal cancer, only two-locus composite genotypes across IKBKB and NFKB1, and IL6 and NFKB1 markers met significance thresholds." (PMID 21129206, 2010). "Previously, we have demonstrated that the IL-6/STAT3 signaling pathway plays a central role in mediating the resistance of rectal cancer to chemoradiotherapy (CRT) and that inhibition of IL-6/STAT3 signaling leads to the sensitization to CRT in vitro and in vivo." (PMID 35267609, 2022). "In conclusion, hapConstructor provided a useful tool to systematically and comprehensively guide our exploration of multilocus SNP combinations in three candidate inflammation-related genes, IKBKB, IL6, and NFKB1 in a U.S. case-control study of colon and rectal cancer." (PMID 21129206, 2010).
Takayasu arteritis (16 papers, 2010 to 2024). A rare inflammatory large-vessel vasculitis primarily affecting the aorta and its major branches, but also other large vessels, causing stenosis, occlusion, or aneurysm. "As well, studies have focused on the genetic association between Takayasu arteritis and IL-6 rs206983713,14." (PMID 35368020, 2022). "The restricted-to-tissue-injury production of cytokines has been shown recently in Takayasu arteritis tissue injury, where IL-6 protein expression was increased in the affected vessels and not in the peripheral blood of patients." (PMID 39594602, 2024). "They demonstrated that the risk allele A of rs2069837 in IL6 represses the expression of GPNMB by recruiting MEF2-HDAC complex, which is enabled through a long-range interchromatin looping in the Takayasu arteritis." (PMID 35368020, 2022). "Tumour necrosis factor inhibitors and anti-interleukin-6 (anti-IL-6) therapies are increasingly being used in Takayasu’s arteritis (TA) patients who are unresponsive to corticosteroids ± conventional immunosuppressive agents." (PMID 31655524, 2020). "Some authors have reported favorable results during treatment with biological agents such as anti-TNF agents, the interleukin-6 antibody tocilizumab, and anti-B cell antibodies such as rituximab in patients with Takayasu’s disease." (PMID 28854963, 2017). "Disease activity and inflammation in Takayasu Arteritis (TA) is thought to be mediated through activated monocytes, macrophages and T-cells that synthetize pro-inflammatory cytokines, including TNF-alpha and IL-6." (PMID 27658465, 2016). "Our finding of failure of IL-6 blockade in the LCWE-model, along with lack of success in studies in human KD and potentially Takayasu arteritis, may suggest that more study is warranted for the use of tocilizumab in certain vasculitides." (PMID 33897686, 2021).
viral hepatitis (16 papers, 2011 to 2024). An acute or chronic inflammation of the liver parenchyma caused by viruses. "One possible cause is the activation of the immune response and the release of cytokines associated with viral hepatitis, such as interleukin-6, interleukin-1β, and tumor necrosis factor-alpha." (PMID 37829687, 2023). "This has previously been attributed to the higher prevalence of risk factors including chronic viral hepatitis, environmental carcinogens like alcohol and smoking, higher testosterone levels and lower levels of IL-6 production in males." (PMID 32774619, 2020). "Associated with most HCC risk factors is an increased circulating interleukin-6 (IL-6) level that functions, amongst other factors, as the best predictor of rapid progression from viral hepatitis to HCC in humans." (PMID 21943068, 2011). "Notably, the search results in the PPI network of key target protein of the intersection targets showed that TLR3, TBK1, IRF3, IL6, were important targets associated with viral hepatitis." (PMID 38322849, 2024). "Furthermore, deficient IL-6 responses were considered to be a major cause of impaired regeneration after hepatectomy in patients with viral hepatitis." (PMID 32050952, 2020). "Besides, TLR3, TBK1, IRF3, IL6, were important targets associated with viral hepatitis." (PMID 38322849, 2024). "Other SNPs are important in the context of viral hepatitis, such as rs1800795 locatednear the promoter region of the Interleukin 6 (IL-6) gene on chromosome 7, whose position can harbor alleles andgenotypes that, through effects on gene transcription, directly affect the levels ofthis cytokine." (PMID 38221914, 2024). "A high level of LPS can promote the secretion of inflammatory cytokines including TNF and interleukin-6 (IL-6), stimulating immune cells and finally may lead to the progression of viral hepatitis." (PMID 37342245, 2023). "Once known as “hepatocyte-stimulating factor” (HSF), IL-6 has been shown to play a key role in chronic inflammatory conditions of the liver that lead to fibrotic lesions, e.g., chronic alcohol consumption or viral hepatitis." (PMID 22629477, 2012). "A comparable mechanism to explain the liver involvement in viral hepatitis has been suggested by the recognized relationship between hepatic inflammation and the rise of IL-1β, TNF-α, and IL-6." (PMID 38983633, 2024).
adenovirus infection (15 papers, 2010 to 2026). "When adenovirus infection, adenovirus invades lung tissue and appears immune response, causing IL-6 to rise rapidly." (PMID 40309168, 2025). "Adenovirus infection can cause inflammation and upregulation of the JAK/STAT pathway, ultimately leading to increased mRNA levels of IL-6, IL-1 β and IFN - α, as well as increased levels of JAK2, STAT3, p-JAK2 and p-STAT3 protein bands." (PMID 41399758, 2026). "A fowl adenovirus, known to cause severe disease in poultry populations, induced elevated mRNA transcription for the same spectrum of pro-inflammatory cytokines detected following mouse and human adenovirus infection (IL-1β, IL-6, IL-8, IFN-α, IFN-β, IFN-γ)." (PMID 35632630, 2022). "In summary, the cytokines and chemokines released in response to adenovirus infection are pro-inflammatory in nature and include cytokines IL-1α, IL-1β, IL-6, IL-8, IFN-γ, IFN-α, and TNF-α and chemokines CCL2, CCL3, and CXCL10." (PMID 35632630, 2022). "Surprisingly, adenovirus infection significantly reduced IL-6 release in cells exposed to either of the three tested bacterial strains by on average more than 50 %." (PMID 27259950, 2016). "In murine peritoneal macrophages and bone marrow derived macrophages, IL-6 expression upon adenovirus infection was mediated by Tlr9." (PMID 20419141, 2010). "Whether high levels of IL-6 and IL-10 in patients with adenovirus infection contribute the worse outcome warrants further investigation." (PMID 32772917, 2020). "Similarly, expression of IL-6 after intravenous administration of adenovirus or adenovirus infection of bone marrow macrophages was dependent on Tlr9 and Myd88, respectively." (PMID 20419141, 2010). "The expression levels of MMP1, IL6, IL8, and PTGS2 increased upon CH25H overexpression via adenovirus infection in human GFs." (PMID 38036731, 2023). "According to previous studies, IL-6, IL-8, and IFN-γ represent the lung immune to response to adenovirus infection, and IL-1α, IL-2, IL-4, IL-5, IL-6, IL-8, IL-17A, IFN-γ, and TNF-α are the major inflammatory cytokines induced by M. pneumoniae infection." (PMID 31316955, 2019). "Notably, neutrophil count and interleukin-6 were significantly positively correlated with disease severity and had high AUC values, suggesting they may be important parameters for early prediction of the progression of mild adenovirus infection to severe disease." (PMID 41902272, 2026). "We speculate that the adenovirus infection of MRC-5 cells leads to CPE and induces the cells to secrete a series of inflammatory factors such as IL-6 and IL-8." (PMID 34960654, 2021). "Furthermore, Trim29-KO BMDCs and BMDMs produced twofold to threefold more IL-6 and TNF-α in response to HSV-1 or adenovirus infection than did WT BMDCs or BMDMs at 12 or 20 h post infection." (PMID 29038422, 2017).